CRP (C-reactive protein)
Diseases named in the same sentence as CRP in open-access papers (continued):
Sharing a sentence is not in itself a finding about the gene and the disease.
Sepsis (continued). "A meta-analysis of PCT and CRP as diagnostic markers of sepsis showed that the sensitivity and specificity of PCT were 0.77 and 0.79, respectively, and the sensitivity and specificity of CRP were 0.73 and 0.61, respectively." (PMID 35309171, 2022). "For the patients included in this analysis, SOFA and CRP values on admission in sepsis were higher than in SIRS, with sodium values only marginally higher." (PMID 35844509, 2022). "The area under the curve (AUC) of CRP was 0.799, and at cut-off level of 69.9 mg/L in prediction of sepsis its sensitivity was 83% and specificity 65%." (PMID 35550043, 2022). "The level of CRP in plasma EVs of sepsis patients was significantly higher than that of the control group." (PMID 35463634, 2022). "The authors concluded that the use of PCT does not provide a significant benefit in the early detection of severe sepsis compared to CRP and IL8." (PMID 35740770, 2022). "In the non-sepsis group, the mean CRP level, WBC, PCT level, and PSEP level were 8 mg/dL, 12577.5 cu/mm, 0.2 ng/mL, and 389.6 pg/mL, respectively." (PMID 35666350, 2022). "Biomarkers such as PCT and CRP can not only be used in predicting sepsis in postoperative patients but can also predict the outcome of septic patients." (PMID 36475186, 2022). "Traditionally, protein biomarkers such as C-reactive protein, procalcitonin, angiopoietins, and serum lactate have been used as biomarkers for sepsis." (PMID 35907902, 2022). "We also aimed to explore its role in the prognosis of sepsis and management and how the levels of CRP and PCT can help with the duration of antibiotic use and the overall prognosis of the patient." (PMID 36475186, 2022). "CRP and Total Leukocyte measurement after 48 hours of clinical symptoms of sepsis enhance the sensitivity and NPV in neonatal sepsis compared with initial assay (with in 6 hrs)." (PMID 37654832, 2022). "Sepsis was more common (18.6% vs. 6.2%, p < 0.001), vasopressors were more frequently required (60.5% vs. 49.3%, p = 0.004), and CRP levels were higher in the decreasing group than in the persistently high group." (PMID 35672868, 2022). "Tracking IL‐6 in connection with CRP has been shown to have prognostic value for early detection of sepsis." (PMID 36176597, 2022). "We also found a significant correlation between the SChE activity and other biomarkers of sepsis (C-reactive protein, procalcitonin, and leukocytes) on ICU admission and during the ICU stay." (PMID 35895337, 2022). "Procalcitonin (PCT), C‐reactive protein (CRP), cytokines, and chemokines have been studied extensively under the previous and revised sepsis definitions." (PMID 35870180, 2022). "MDW is expected to serve as a useful indicator for early screening of sepsis in conjunction with CRP and PCT." (PMID 36538555, 2022). "In this study, CRP was assessed twice: once within six hours of the onset of clinical sepsis symptoms and again 48 hours later." (PMID 37654832, 2022). "Overall, 131 term and preterm babies were evaluated for sepsis and had CRP performed as part of their evaluation, between November 2014 and April 2015." (PMID 36517750, 2022). "In all infants exhibiting clinical signs of sepsis, CRP 1, CRP 2, Total Leukocyte count 1 (WBC1), Total Leukocyte count 2 (WBC2), and blood culture were conducted." (PMID 37654832, 2022). "The currently popular methods to identify sepsis clinical outcome are the utilize of several serum biomarkers, i.e., CRP, PCT, SSA, lactate, and HBP, but the unsatisfied sensitivity and specificity limit their applications in clinical practice." (PMID 35291488, 2022). "It has been reported that CRP can act as a marker of fever, bloodstream infection, and sepsis in immunocompromised patients." (PMID 35463661, 2022). "We hope that the proposed aptasensor paves the way for a new opportunity to fabricate a cost-effective, selective, and sensitive device to measure the CRP biomarker as one of the key biomarkers in sepsis diseases." (PMID 35159761, 2022).
Sepsis (continued). "In the current study, an effort has been made to know the various etiological agents responsible for NS and correlate the efficacy of the sepsis score and the sepsis screening parameters like CRP in estimating and reducing antibiotic therapy duration." (PMID 36246087, 2022). "MiR-27a-3p is DE between ward and ICU patients, was correlated with leukocytes and CRP, and represents a potential in regulation of inflammatory response in sepsis." (PMID 35938548, 2022). "The optimal cut-off value of the CRP level to discriminate between sepsis and septic shock was 6.62 mg/L (sensitivity, 65.7%; specificity, 46.8%; AUC, 0.559; 95% CI 0.498–0.618; p = 0.088)." (PMID 34983420, 2022). "There were also high values for SII or CRP + NLR in Groups I and II, which were associated with sepsis, shallow but extensive abscess formation, and inflammation that spilled into the deep anatomic space." (PMID 36503406, 2022). "Newborns with suspected sepsis with positive blood culture and raised CRP needed a longer duration of antibiotic therapy." (PMID 36246087, 2022). "On the other hand, CRP level correlates with the severity of the condition, and its decrease during sepsis therapy correlates with the effectiveness of the treatment." (PMID 35615626, 2022). "A recently published study showed a significant digitoxin-mediated reduction in CRP levels in mice suffering from sepsis, providing a small piece of evidence that cardiac glycosides are also capable of inhibiting CRP synthesis in mice." (PMID 35407370, 2022). "If a combination of CRP and sFAS increases sensitivity of sepsis diagnosis to 88% compared to 87% for PCT alone as in our study population, routine use of these biomarker combinations should be carefully evaluated also from economical aspects." (PMID 35550043, 2022). "PCT was found the best to distinguish sepsis with AC and CRP was found the best to suggest an infection." (PMID 35340766, 2022). "Infection marker of PCT was showing increased trend, and CRP was shoving a peak value in sepsis group (p < 0.05)." (PMID 34825737, 2022). "CRP concentrations are often used as an indicator to reflect the severity of sepsis for the reason that increased CRP levels exhibit a close association with high infections and mortality rates in critically ill patients." (PMID 35656863, 2022). "We found that patients with sepsis and septic shock had the highest CRP levels on day 2, whereas patients with burn injury presented with the highest CRP concentrations by day 5–6." (PMID 35453598, 2022). "Compared to the CTRL group, patients with sepsis had higher levels of C-reactive protein (CRP), interleukin- (IL-) 6, and heparin-binding protein (HBP)." (PMID 35633656, 2022). "With the cutoff set at even higher CRP concentrations >10 mg/L, the specificity in detecting any clinical sepsis (both EOS and LOS) by CRP concentrations >10 mg/L was 100%, given the definition of clinical sepsis in this work." (PMID 36233706, 2022). "While circulating markers, such as C-reactive protein (CRP) and lactate, are currently in clinical use, they have relatively weak predictive power relative to potentially life-threatening outcomes such as sepsis." (PMID 35081105, 2022). "Infection markers such as PCT and CRP are commonly used for the adjuvant diagnosis of sepsis, and their role in the diagnosis and prediction of sepsis is still being explored." (PMID 34825737, 2022). "In contrast, sepsis cohorts had significantly higher levels of C-reactive protein [52.8 (34-73.3) vs. 2.60 (1-3.65), p < 0.001]." (PMID 35669402, 2022). "In previous studies, the differential value of sTREM-1 was evaluated in the diagnosis of sepsis in populations of systemic inflammatory response syndrome and outperformed CRP and procalcitonin." (PMID 35862959, 2022). "Routine neonatal clinical sepsis diagnosis mainly depends on blood culture, serum procalcitonin, and CRP levels." (PMID 35770922, 2022).
Sepsis (continued). "The most studied biomarkers in the pediatric sepsis context have been C-reactive protein, procalcitonin, and lactate." (PMID 35223703, 2022). "During systemic inflammation, the incidence of atrial fibrillation increases, especially in sepsis, and plasma C-reactive protein (CRP) levels increase before the onset of atrial fibrillation." (PMID 36405582, 2022). "The invaluable properties of PCT and CRP have led to their use in diagnostics as biomarkers of systemic inflammation and sepsis." (PMID 35149284, 2022). "To increase overall performance for discriminating sepsis we combined CRP with IL-10 and found a greater AUC of 0.860 (Cl 95% 0.756-0.931), while increasing specificity (98%) but not sensitivity (75%)." (PMID 35582414, 2022). "Especially, the success of antibiotic therapy in bacterial infection and sepsis is usually determined by measuring CRP levels in addition to clinical evaluation." (PMID 35407379, 2022). "Hematological and laboratory data on D0 from the sepsis group were characterized by higher immature neutrophil count and immature/total neutrophil ratios, CRP, and direct bilirubin in comparison to controls." (PMID 36368184, 2022). "Studies in patients with sepsis have demonstrated that some composite inflammatory parameters, such as the CRP/SA ratio, have a higher predictive capacity than CRP alone." (PMID 35740416, 2022). "To assess this suggestion, we compared the functional phenotypes of mouse and rat CRP KO in two acute inflammatory diseases, i.e., acetaminophen-induced liver failure and lipopolysaccharide (LPS)-induced sepsis." (PMID 35338247, 2022). "In this study, more intraoperative blood transfusion was found in conventional open surgery, accompanied by a higher rate of postoperative sepsis, a qSOFA of ≥2, and delayed normalization of CRP." (PMID 35884964, 2022). "In line with previous study, CRP was poor for predicting sepsis in children compared to MPV.We suggested that CRP is not superior to using MPV for predicting weaning failure." (PMID 35614411, 2022). "From January 2020 onwards, we start PTX in cases of suspected sepsis when IL-6 levels are above 500 pg/mL and/or CRP levels are above 50 mg/mL at onset." (PMID 35786750, 2022). "Eosinopenia has also been shown to be predictive of sepsis in the ED settings, with a higher performance than other markers such as CRP and PCT." (PMID 35346082, 2022). "Patients undergoing conventional open surgery encountered more postoperative sepsis (p = 0.030), a higher qSOFA score (p = 0.044), and prolonged-time for CRP normalization (p = 0.001)." (PMID 35884964, 2022). "The most important clinical concern about CRP targeting is the danger of immunosuppression with consecutive bacterial or viral infection and sepsis." (PMID 35407379, 2022). "The predictive ability for MOF and sepsis was assessed using the Receiver Operating Characteristic (ROC) comparing to C-reactive protein (CRP)." (PMID 34065206, 2021). "Other sepsis markers we used in clinics nowadays (such as c-reactive protein, procalcitonin, serum lactate) are far from being specific to sepsis, but they have been useful in diagnosing sepsis patients." (PMID 34604260, 2021). "What is more, CRP abnormalities are more common in infections, such as bacterial meningitis, sepsis, and other related encephalopathy." (PMID 34868532, 2021). "A previously healthy male was rushed into a hospital critically ill with confusion, sepsis, and acute respiratory distress syndrome only 43 h after having a normal chest X-ray and with blood samples showing only minimally elevated C-reactive protein." (PMID 35076575, 2021). "During the first three days of life, CRP, leucopenia, and neutropenia were comparably good tests while after three days of life; CRP was the single best test in early detection of neonatal septicemia." (PMID 34899922, 2021).
Sepsis (continued). "The present study, which compared patients with sepsis alone vs. sepsis and ARDS, identified much higher levels of serum FGF21 and pro-inflammatory factors (PCT, CRP, IL-6, and TNFα) in the Sepsis + ARDS group." (PMID 34154595, 2021). "The observed successful closure rates and effective sepsis control of EVT were accompanied by a rapid decrease in inflammation markers (CRP and white blood cell count)." (PMID 33593301, 2021). "Using binary logistic regression analysis adjusted by age and gender, both GPR174 mRNA (OR = 0.004, P = 0.003) and CRP (OR = 1.010, P = 0.031) at D7 were found to be independent predictors of 90-day mortality in patients with sepsis." (PMID 35173706, 2021). "The diagnostic accuracy of PSP, CRP and PCT for the diagnosis of sepsis at the time the EAC identified it were similar." (PMID 33879189, 2021). "The CRP/Alb ratio was found to predict disease severity and 90-day mortality in patients with sepsis." (PMID 34900028, 2021). "The combination of blood culture, clinical assessment (sick appearance) with CRP > 0.75 mg/dl or NLR > 1.5 identified 33 of 33 infants with sepsis (100%) with only 18 of 72 (25.0%) control infants considered as possible sepsis beyond 24 h." (PMID 34490157, 2021). "Contrary to this study, our results showed that the sPD1 level is positively correlated with the level of CRP andPCT in patients with sepsis." (PMID 33650816, 2021). "Diagnostic performance of WBC count, CRP, PCT, and MDW for predicting sepsis according to immune status." (PMID 33857210, 2021). "The laboratory indexes of the clinical diagnosis of sepsis include C-reactive protein (CRP), procalcitonin (PCT), and IL-6." (PMID 33505221, 2021). "CRP is an acute-phase inflammatory serum protein that responds rapidly to infection and is highly accurate in predicting sepsis-suspected mortality in patients." (PMID 33869237, 2021). "PCT has been proven by many studies to be superior to CRP in the diagnosis of sepsis and intensity of infection." (PMID 34666725, 2021). "Neutrophil CD64 was included in this study as it is a known marker of neutrophil activation and is also a strong candidate for diagnosing sepsis, outperforming CRP and procalcitonin." (PMID 34065206, 2021). "Overall, as a diagnostic test, IgM has equivalent or better specificity and sensitivity for sepsis with and AUC of 0.73 compared with CRP with varying AUC of 0.6–0.9 reported for severe sepsis." (PMID 34830673, 2021). "CRP and PCT values can be used as independent risk factors for the prognosis of patients with sepsis." (PMID 34233608, 2021). "In the current study, hs-CRP levels in sepsis were significantly higher (P < 0.001) than those in both healthy and diseased controls." (PMID 34691286, 2021). "In this visual plot, the probability of developing sepsis was found to increase significantly as the values of IG%, CRP, and %TBSA increased." (PMID 34915849, 2021). "The novel finding of this study is the persistent derangements of LDL, total cholesterol, Lp(a), and high sensitivity (cardiac) CRP up to two years after sepsis." (PMID 34869619, 2021). "Multiple biomarkers have been used as diagnostic and/or prognostic biomarkers predicting outcomes for patients with infection/sepsis, including lactate, CRP, cluster of differentiation 64, proadrenomedullin, interleukin-6, procalcitonin, and many others." (PMID 34439240, 2021). "An in comparison late biomarker, such as CRP, at 24 and 48 h after the initial presentation can accurately confirm the infection and allow discontinuation of antibiotics in non-sepsis cases." (PMID 34640557, 2021). "Although there are clinical guidelines and many laboratory tests to diagnose sepsis, e.g., the C-reactive protein (CRP) test, procalcitonin (PCT) test, and white blood cell (WBC) count, their specificity is unsatisfactory." (PMID 34675320, 2021). "Initially, the patient was misdiagnosed with sepsis because of elevated C-reactive protein and procalcitonin levels." (PMID 35003816, 2021).
Sepsis (continued). "In this case, CRP serum concentration rises above 5 μg/mL in about 6 h after stimulation and peaks 48 h after sepsis onset, while studies have demonstrated the importance of repetitive CRP measurements in monitoring the treatment response in infected neonates." (PMID 34436070, 2021). "Previous studies reported the correlation between serum C-reactive protein level and mortality of sepsis patients." (PMID 34067038, 2021). "Our group recently published data on PSP’s excellent predictive power to detect sepsis and septic shock (Sepsis-3) in burn patients—outperforming PCT and CRP by its steeper and earlier rise prior to the critical onset of sepsis." (PMID 34442346, 2021). "CRP levels were intensively higher in the AOSD group than in the sepsis group (102.71±67.04 mg/L vs 69.81±56.70 mg/L, p=0.003)." (PMID 33886787, 2021). "Urinary C-reactive protein comes from blood and can substitute for serum C-reactive protein in sepsis diagnosis." (PMID 34675320, 2021). "In our meta-analysis, the best tool to assess sepsis-related coagulopathy seemed to be CRP elevation and, to a lesser extent, procalcitonin—with regards to the risk of a false positive result for the latter." (PMID 34948552, 2021). "• Change in CRP, a putative marker of sepsis at 72 hours (continuous) and microbiological cure (seven-day) (binary), alone and as a composite with seven-day survival." (PMID 37519413, 2021). "Overall, insufficient evidence supports the accuracy of presepsin compared with traditional biomarkers, such as procalcitonin or CRP to diagnose sepsis." (PMID 33803628, 2021). "In summary, PCT, CRP, NLR, MLR, PLR, and CRP*PCT can be used as independent risk factors affecting the prognosis of patients with sepsis." (PMID 34233608, 2021). "A systematic review published in 2018 concluded that PCT is more sensitive than CRP but that doing the two tests together would result in greater sensitivity and would be more useful in the detection of sepsis." (PMID 34912626, 2021). "C-reactive protein (CRP) is an acute inflammatory factor and is the most import biomarker of sepsis." (PMID 34630395, 2021). "Currently, studies have shown the roles of various biomarkers such as cell surface markers, cytokines, procalcitonin (PCT), and C-reactive protein (CRP) in the diagnosis, severity, and prognosis of sepsis." (PMID 34095029, 2021). "In another study conducted in an emergency department, which included patients older than age 65 years, the CRP and erythrocyte sedimentation rate were more reliable markers for differentiating sepsis from SIRS compared with PCT, WBC, and interleukin-6 levels." (PMID 34344141, 2021). "The use of CRP and IL-6 as biomarkers of sepsis or infection after solid organ Tx is therefore doubtful, and PCT should be used with caution only in specific groups of patients (e.g., induction immunosuppression with basiliximab and rituximab)." (PMID 33505219, 2021). "Biomarkers associated with the innate immune system, especially soluble biomarkers such as cytokines IL-6 and IL-10, CRP, and procalcitonin have shown variable ability to identify hyper inflammation and/or sepsis." (PMID 34065206, 2021). "The elevated microerythrocyte sedimentation level was seen with sepsis types and C-reactive protein." (PMID 34899922, 2021). "Conversely, the serum concentration of CRP was significantly higher in dogs with sepsis than in dogs with trauma and in clinically healthy dogs; a significant difference was also found between dogs with trauma and clinically healthy dogs." (PMID 34072427, 2021). "Novel biomarkers for sepsis are required because the existing inflammatory biomarkers for its diagnosis, such as C reactive protein (CRP), procalcitonin (PCT), and interleukin (IL)-6, have respective shortcomings in identification of sepsis onset." (PMID 34055659, 2021). "Plasma CRP levels were 227.0 ± 88.6 mg/L for sepsis patients (n = 30) vs. 0.7 ± 0.4 mg/L for healthy individuals (n = 5)." (PMID 33772103, 2021).